YTHDF1 (YTH N6-methyladenosine RNA binding protein F1)
Diseases named in the same sentence as YTHDF1 in open-access papers (continued):
Sharing a sentence is not in itself a finding about the gene and the disease.
tumor (continued). "The analysis performed to explore the influence of YTHDF1 expression on clinical characteristics revealed that YTHDF1 expression in OS patients with a tumor diameter < 5 cm was significantly lower than in patients with a tumor diameter ≥ 5 cm." (PMID 35156522, 2022). "Depletion of YTHDF1 in DCs in mouse models enhances cross-presentation of tumor antigens, promotes their cross-priming with CD8+ T and increases the infiltration of neoantigen-specific CD8+ T cells in the tumor microenvironment, thus enhancing antitumor immunity." (PMID 36085064, 2022). "These collectively suggest that YTHDF1 manipulation might modulate tumor immunogenicity via its effect on DCs." (PMID 35193930, 2022). "YTHDF1 may act as a hopeful pan-cancer immune biomarker, as well as a novel promising marker for tumor immunotherapy." (PMID 36035182, 2022). "YTHDF1 depletion in dendritic cells could enhance the cross-presentation of tumor antigens and cross-priming of CD8+ T cells." (PMID 35331183, 2022). "Additionally, the tumor volume and weight in the YTHDF1-KO group were smaller than those in the control group." (PMID 36439881, 2022). "For instance, YTHDF1 is associated with HCC maintenance, where HIF-1α swells YTHDF1 transcription by mediating HIF-1α-binding site 1 (HBS1) and HBS3 site of HIF-1α interacting with the YTHDF1 promoter region under hypoxic conditions, which zooms autophagy-related tumor growth and metastasis." (PMID 35864970, 2022). "Mechanistically, RNA-sequencing revealed that the of loss YTHDF1 mediates the overexpression of interferon-γ receptor 1 and JAK/STAT1 signaling pathway in tumor cells, which may contribute to restoring sensitivity to antitumor immunity." (PMID 35884552, 2022). "The reader YTHDF1 promotes tumor progress by influencing ATG2A, ATG14, and HIF-1α." (PMID 36059442, 2022). "Although the role of YTHDF1 or YTHDF2 in the tumor immune microenvironment may differ depending on cell type, no such study has been performed." (PMID 36479088, 2022). "YTHDF1 expression is correlated to multiple immune infiltrating cells, which may impact the tumor immunity of ESCA by affecting the infiltration of dendritic cell." (PMID 35401696, 2022). "Studies have shown that m6A methylation of dendritic cells and YTHDF1 regulate anti-tumor immunity, further supporting the view that decreased YTHDF1 expression may be related to T cell inflammation and tumor microenvironment." (PMID 35875124, 2022). "In addition, DCs tumor infiltration was negatively correlated with the YTHDF1 mRNA expression in TCGA cohort (p<0.0001)." (PMID 35193930, 2022). "Consistently, YTHDF1 knockdown impeded tumor growth significantly." (PMID 35279688, 2022). "Intriguingly, YTHDF1 as a target of tumor immune regulation has also attracted much attention." (PMID 36035182, 2022). "In summary, we speculate that IGFBP1 may cooperate with YTHDF1 to mediate methylation modification, thereby inhibiting the activation of DCs and cytotoxic T lymphocytes, hindering the anti-tumor immune response in tumors." (PMID 35875124, 2022). "The results indicated that the protein level of YTHDF1 in OS tumor tissues was also increased." (PMID 35156522, 2022). "YTHDF1 mediated the increase of lysosomal proteases and tumor antigen degradation in dendritic cells and could weaken anti-tumor response and disable CD8+ T cells." (PMID 35646049, 2022). "It was found that the tumor size of YTHDF1 knockout mice is much smaller than that of wild type, and the immunoreactivity of M6A knockout mice was stronger than that of wild type, indicating that YTHDF1 can be used as an important target of immunotherapy against clinical tumors." (PMID 33428597, 2021). "Moreover, YTHDF1 also plays an important role in oncogenesis and tumor progression in various cancers." (PMID 34026603, 2021). "Moreover, YTHDF1 knockout in classic dendritic cells was shown to increase the cross-presentation of tumor antigens and the cross-priming of CD8+ T cells." (PMID 34359836, 2021).
tumor (continued). "Considering the crucial role of EMT in tumor metastasis, it was worth to investigate whether YTHDF1 was involved in the regulation of the EMT process of HCC cells." (PMID 34088349, 2021). "Moreover, METTL3-deficiency in macrophages impairs the YTHDF1-mediated translation of SPRED2, which enhances the activation of NF-kB and STAT3 through the ERK pathway, leading to increased tumor growth and metastasis." (PMID 34526985, 2021). "Furthermore, hematoxylin and eosin (H&E) staining of the subcutaneously implanted tumors showed the morphology of tumor cells, and IHC staining confirmed the downregulation of YTHDF1 in the shYTHDF1 group." (PMID 34088349, 2021). "Notably, several specific m6A regulators play dual roles in cold tumor formation, such as METTL3, METTL14, and YTHDF1, suggesting the exact role m6A RNA modification-mediated cold tumor formation is tumor-type dependent." (PMID 34616742, 2021). "YTHDF1 expression was significantly correlated to tumor-infiltrating immune cells, indicating that it might contribute to the complexity and diversity of immune microenvironment." (PMID 34434939, 2021). "In addition, patient tumor samples that had low YTHDF1 expression had higher tumor-infiltrating CD8+ T cells." (PMID 33535484, 2021). "The m6A RNA modification, such as YTHDF1, was reported to regulate anti-tumor immune responses." (PMID 33796449, 2021). "Our result suggested that YTHDF1 also played a tumor-promotor role in LGG." (PMID 35069679, 2021). "ALKBH5 and YTHDF1 could possibly play a potential role in the transformation of cold to hot tumor in COAD." (PMID 34079761, 2021). "Ythdf1-deficient mice showed an elevated antigen-specific CD8+ T cell antitumor response, and loss of YTHDF1 in classical dendritic cells enhanced the cross-presentation of tumor antigens and the cross-priming of CD8+ T cells in vivo." (PMID 34804948, 2021). "Furthermore, Our previous report found that YTHDF1 suppresses CD8+ T cell antitumor response through controlling cross-presentation of tumor antigens." (PMID 34324489, 2021). "The data suggest that YTHDF1 may have contributed to the regulation of tumor immune microenvironment." (PMID 33692959, 2021). "We herein found that YTHDF1 could promote USP14 protein translation in a m6A-dependent manner and USP14 overexpression reversed the tumor suppressive effects caused by YTHDF1 knockdown in GC cells." (PMID 33791305, 2021). "Furthermore, YTHDF1 inhibits the function of antitumor immune cells in the tumor microenvironment (TME) by acting on the infiltrated level of CD8+ T cells and natural killer cells." (PMID 34026603, 2021). "The biological effect of YTHDF1 was further elucidated in vivo by orthotopic tumor transplantation." (PMID 33619246, 2021). "Furthermore, YTHDF1-knockdown mice had stronger response to tumor antigen-specific CD8+ T cells than wild-type mice; knockdown of YTHDF1 in classic DC cells enhanced the cross-presentation of tumor antigens in vivo and the cross-activation of CD8+ T cells." (PMID 34956201, 2021). "We herein found that IU1 as an inhibitor of USP14 could repress cell growth and restore the tumor-promoting effects induced by YTHDF1 in GC cells." (PMID 33791305, 2021). "Therefore, we have no specific and complete cases with data to identify the benefit of anti-YTHDF1 targeting drugs in the survival of cancer models or inhibiting tumor growth." (PMID 34026603, 2021). "Similarly, ATG2A or ATG14 downregulation in Hep3B cells counteracted the stimulative effect of YTHDF1 overexpression on tumor growth." (PMID 33619246, 2021). "Moreover, the CD8+ T cell-mediated tumor antigens-specific immune response is elevated in Ythdf1−/− mice owing to the enhancement of cross-presentation of DCs." (PMID 33746967, 2021).
tumor (continued). "YTHDF1 was correlated with an unfavorable clinical stage and tumor size." (PMID 34359836, 2021). "The tumor volume of the YTHDF1 knockdown group was smaller than that of the control group." (PMID 33816306, 2021). "TRMT10C (‘writer’), YTHDF1 (‘reader’) and YTHDC1 (‘reader’) genes had the greatest number of mutations, with missense mutations potentially leading to impaired function, affecting m1A signaling in cells and causing physiological disorder in tumour cells." (PMID 32934298, 2020). "When non-small cell lung cancer (NSCLC) cells were in a normoxia state, overexpression of YTHDF1 promoted tumor cells proliferation and xenograft tumor formation by augmenting the translations of m6A-marked CDK2, CDK4, and cyclinD1, three key regulators in the G0/G1 cell cycle transition." (PMID 32276589, 2020). "In addition, the expressions of YTHDF1 were higher in the NSCLC tumor cell lines than that in the control cells BEAS-2B." (PMID 32106857, 2020). "In HCC cells, YTHDF1 could dramatically accelerate the translation of Snail mRNA via an m6A-dependent manner, thus contributing to tumor metastasis." (PMID 32276589, 2020). "A comparison of all results showed that the HNRNPC, WTAP, YTHDF2, and YTHDF1 were up-regulated in tumor samples and might influence the tumorigenesis of GBM." (PMID 33134160, 2020). "Moreover, stable knockdown of YAP inhibited xenograft tumor growth mediated by YTHDF1 overexpression in vivo." (PMID 32106857, 2020). "m6A modification can modulate immune response induced by tumor neoantigens via YTHDF1." (PMID 32276589, 2020). "By contrast, the expression of YTHDF1 was higher in tumor tissues than in normal tissues." (PMID 32106857, 2020). "However, when NSCLC cells were treated with cisplatin, a chemotherapy drug inducing the reactive oxygen species (ROS) accumulation, YTHDF1 was decreased and led to cisplatin resistance in tumor cells via regulating the Keap1-Nrf2-AKR1C1 axis." (PMID 32276589, 2020). "We used xenograft tumor formation to examine the in vivo function of YTHDF1." (PMID 31653849, 2019). "Furthermore, we found the YTHDF1 expression level was correlated with clinical statistical, such as tumor depth and tumor size." (PMID 31131257, 2019). "Additionally, the online database showed that the YTHDF1 gene has a cancer-promoting potential score of B, while its knockdown markedly suppressed xenograft tumor growth in a mouse model." (PMID 31131257, 2019). "Consistently, a lower proliferation rate evidenced by Ki67 staining and an increase of CC3-positive cells were detected in lung tumors from KPY (or KY) mice compared to the KP (or K) mice, suggesting that YTHDF1 deletion had an inhibitory effect on tumor cell growth in vivo." (PMID 31653849, 2019). "Considering that the present study indicated that YTHDF1 is involved in malignant nature of cancer, we propose that a group of miRNAs which targeting on 3′ untranslated region might play a role in the tumor suppressor function." (PMID 29484125, 2018). "To further elucidate whether the upregulation of p27 is the key factor inhibiting tumor cell proliferation following YTHDF1 knockdown, we conducted a subsequent knockdown of p27 in indicated cells already subjected to YTHDF1 knockdown and found that p27 knockdown countered the effect of YTHDF1." (PMID 40251202, 2025). "YTHDF1 is a powerful reader for m6A modification, which translationally controls RNA transcripts and participates in many physiological and pathological processes, such as tumor growth and metastasis, antitumor immune responses, axon guidance, and the proliferation of native T cells." (PMID 39936952, 2025). "Mechanistically, Ythdf1-deficient tumors exhibit enrichment of mature DCs (↑MHC-II, ↑IL-12), enhanced CD4+/CD8+ T-cell infiltration, and increased IFN-γ production, while activating the tumor cell IFN-γR1–JAK/STAT1 pathway, thereby heightening susceptibility to immune clearance." (PMID 41403953, 2025).
tumor (continued). "Notably, tumor-intrinsic YTHDF1 depletion can elevate PD-L1 levels in vivo yet still sensitize tumors to immune attack—an apparent inconsistency that likely reflects dominant effects on the antigen-presentation axis and T-cell priming that outweigh PD-L1 upregulation per se." (PMID 41280938, 2025). "Similarly, YTHDF1 absence in TAMs promotes anti-tumor immunity in the presence of CD8 + T cells." (PMID 38898486, 2024). "To test this, we measured YTHDF1 expression in tumor-infiltrating DCs from Sting-KO mice and found that IR did not significantly induce YTHDF1 expression in DCs from Sting-KO mice compared with DCs from WT mice, suggesting that Sting KO abolished IR-induced YTHDF1 in DCs." (PMID 39325547, 2024). "Therefore, METTL3 collaborates with YTHDF1 to promote tumor progression and attenuate the efficacy of tumor therapy by targeting the SPRED2/ERK/NF-kB-STAT3 signaling pathway, highlighting the clinical possibilities of using METTL3 as a target in tumor immunotherapy." (PMID 39416774, 2024). "Additionally, YTHDF1 promotes tumor immune evasion by enhancing PD-L1 expression." (PMID 38902779, 2024). "Furthermore, the combination treatment of YTHDF1 knockdown and anti-PD-L1 led to a complete tumor regression that overwhelmed the monotherapy groups evaluated, indicating that YTHDF1 depletion in combination with an ICI is a novel strategy to enhance the therapeutic efficacy." (PMID 36810108, 2023). "In tumor cells, YTHDF1 deficiency increased PD-L1 expression in vivo but not in vitro." (PMID 36650153, 2023). "Considering its the potential effects on immune evasion, YTHDF1 siRNA is packaged in engineered small extracellular vesicles (sEVs) for GC treatment, producing anti-cancer efficiency by achieving self-presentation of the immunogenic tumor cells to stimulate robust cytotoxic T lymphocytes responses." (PMID 37015927, 2023). "Additionally, at an in vivo level, CD8α+ and CD11b+ DCs from draining lymph nodes (DLNs) of B16-OVA- or MC38-OTIp-tumour-bearing Ythdf1−/− mice showed a substantially augmented cross-priming capacity as compared with those collected from the wild mice when both co-cultured with OT-I T cells." (PMID 38136940, 2023). "Recent studies have reported that YTHDF1-3 could act as tumour markers in RCC." (PMID 37284313, 2023). "Here, we demonstrated that tumor-intrinsic YTHDF1 initiates translation of lysosomal genes and promotes proteins expression by increasing the ribosomal loading of m6A-modified mRNA, which is critical for maintaining intact lysosomal function and degrading tumor antigen and MHC-I." (PMID 36650153, 2023). "In addition, YTHDF1 also exerts regulatory effects on tumors through multiple signaling pathways, and numerous studies have confirmed its ability to assist in the reprogramming of the tumor cell-related metabolic processes." (PMID 38202722, 2023). "Moreover, YTHDF1 also regulates tumor microenvironment (TME) and participates in immune regulation." (PMID 37598390, 2023). "However, the regulatory role of YTHDF1 in tumor-related lncRNA translation is rarely studied." (PMID 36710350, 2023). "We can trust that YTHDF1 might be a novel moderator in tumor immunotherapy." (PMID 37598390, 2023). "Indeed, the depletion of CD8+ cells largely rescued Ythdf1-KO tumor growth." (PMID 36650153, 2023). "In addition, YTHDF1 expression was significantly associated with various features of CRC such as depth, lymph node metastasis (LNM), tumor stage, and poor prognosis, suggesting that its expression may be a useful independent prognostic factor for CRC." (PMID 37833468, 2023). "In addition, YTHDF1 protein levels increased steadily with increasing HPSCC tumor grade." (PMID 37612282, 2023). "In addition, METTL3 deficiency impairs YTHDF1-mediated SPRED2 translation, which enhances NF-κB and STAT3 activation via the ERK pathway, resulting in increased TAM-induced Treg infiltration into TME and tumor metastasis." (PMID 35794625, 2022).
tumor (continued). "Therefore, targeting the YTHDF1-m 6 A-ARHGEF2 axis may be a promising therapeutic strategy to inhibit tumor growth, invasion, and metastasis." (PMID 36347025, 2022). "For example, YTHDF1 induces lysosomal protease expression by recognizing its m6A methylation-tagged mRNA and enhancing translation efficiency, further resulting in the inability of DCs to consistently induce tumor neoantigen production and impeding antigen-specific activation of CD8+ T cells." (PMID 35794625, 2022). "YTHDF1 could act as an oncogene or a tumor suppressor gene in tumors." (PMID 35197112, 2022). "High expression of YTHDF1 in tumor tissues implies that YTHDF1 might play an oncogenic role in GC." (PMID 35193930, 2022). "In addition, loss of YTHDF1 mediated the overexpression of IFNGR1 and JAK1/2-STAT1 pathway in tumor cells, which might contribute to restored sensitivity to antitumor immune response." (PMID 35193930, 2022). "All above results suggested that down-regulation of YTHDF1 might inhibit OS tumor growth." (PMID 35156522, 2022). "Interestingly, a recent study found a N6-methyladenosine (m6A) modification on GMEB2 mRNA, which may be recognized by the m6A reader YTHDF1 in tumour cells." (PMID 36551532, 2022). "Conversely, YTHDF1 deficiency in gastric cancer promotes the recruitment of mature DCs, which further stimulate MHCII expression and IL-12 secretion, in turn, increasing CD4+ and CD8+ T cell infiltration and IFN-γ secretion that potentially contribute to restoration of tumor immune sensitivity." (PMID 35794625, 2022). "YTHDF1 may be a potential therapeutic target and an important mediator of tumor immune evasion." (PMID 34054840, 2021). "It has been reported that YTHDF1 can promote lysozyme in dendritic cells to regulate the degradation of tumor neoantigens, and the key to this process is that YTHDF1 can accurately recognize the m6A modification process of tumor neoantigens and enhance their translation level." (PMID 34993195, 2021). "Similarly, YTHDF1 deficiency could inhibit NSCLC cell proliferation and xenograft tumor formation by regulating the translational efficiency of cell-cycle-related genes, such as CDK2, CDK4, and cyclin D1." (PMID 34359836, 2021). "Moreover, YTHDF1 expression is related to all of the examined marker genes of CD8+ T cells, monocytes, tumor-associated macrophages (TAMs), M2 macrophages, Th1 cells, and other known immune stimulatory and immune suppressive cytokines, which proves the potential immune function of YTHDF1 in PRAD." (PMID 34026603, 2021). "Therefore, YTHDF1 plays a key role in tumor immune evasion by regulating the activity of DCs." (PMID 34103054, 2021). "Furthermore, PD-L1 expression was increased in tumor cells from Ythdf1−/− tumor-bearing mice, anti-PDL1-treated on Ythdf1−/− tumor-bearing mice made tumor disappeared, the simultaneous depletion of PD-L1 and YTHDF1 was beneficial to the improvement of tumor immune microenvironment." (PMID 34630412, 2021). "Furthermore, YTHDF1 overexpression promoted xenograft tumor growth in vivo." (PMID 32106857, 2020). "Next, we investigated whether YTHDF1 increased NSCLC tumor growth and metastasis by regulating YAP." (PMID 32106857, 2020). "Moreover, the potential target genes regulated by YTHDF1 protein may be related to tumor cell cycle, degradation of various amino acids and lipid metabolism, while the abnormal physiological functions may be related to the occurrence and development of HCC." (PMID 32974160, 2020). "YTHDF1 promotes lysosomal proteases-directed-degradation of neoantigens in dendritic cells by recognizing their m6A modification and enhancing their translation, thereby suppressing dendritic cells presenting tumor neoantigens to T cells and promoting tumor cells to evade immunosurveillance." (PMID 31801551, 2019). "In addition, the expression level of YTHDF1 is related to tumour depth and size." (PMID 31810483, 2019).